FDPS (farnesyl diphosphate synthase)
Diseases named in the same sentence as FDPS in open-access papers (continued):
Sharing a sentence is not in itself a finding about the gene and the disease.
tumor (continued). "At present, anti-tumor drugs targeting the MVA pathway can be roughly divided into three categories according to their targets: anti-HMGCR, anti-FDPS and anti-SREBP2." (PMID 37005437, 2023). "GO enrichment analysis of a TNBC tumor with elevated expression of ENO1 and FDPS revealed the highest enrichment in functional categories associated with the cell cycle and mitosis." (PMID 37190091, 2023). "Mechanistically, we identified FDPs regulate glucose-6-phosphate dehydrogenase (G6PD) by RNA sequencing, bioinformatics prediction, and rescue experiments, indicating its involvement in glycolysis regulation in tumour cells." (PMID 41667936, 2026). "Additionally, FDPS was significantly positively correlated with lymph node metastasis in the TCGA-BLCA cohort and with tumor T stage in the GSE32548 cohort." (PMID 39521858, 2024). "As a result, we found that FDPS knockdown significantly reduced CCL20 protein expression in subcutaneous xenograft model, while overexpression of FDPS remarkably promoted CCL20 protein levels in syngeneic tumour tissues." (PMID 32596949, 2020). "To demonstrate increased activity of the MVA pathway in CSCs of CRC, we cultured tumor spheres and found significantly elevated protein and mRNA levels of key enzymes of the MVA pathway, including HMGCR, FDPS, GGPS1, and SQLE, in tumor spheroids compared to 2D adherent cultured cells." (PMID 32911743, 2020). "Bone metastasis inhibitor zoledronic acid has the potential to prevent prenylation of small-G proteins by inhibition of farnesyl-diphosphate synthase, suggesting the anticancer effect of the agent not only on the metastases, but directly on the primary tumor as well." (PMID 27780929, 2016).
cancer (43 papers, 2014 to 2026). A tumor composed of atypical neoplastic, often pleomorphic cells that invade other tissues. "Besides, four sex-biased exon skipping events in cancer therapeutic target genes (FDPS, FGFR1, CDK4, and IMPDH2) could cause the loss of partial protein function, which may contribute to a differential drug response rate in male and female patients." (PMID 39175079, 2024). "Furthermore, it has been shown that HTyr exerted its anti-proliferative and pro-apoptotic effects in human HCC cells by inhibiting the expression of fatty acid synthase (FAS) and farnesyl diphosphate synthase (FPPS), whose higher expression was associated with higher aggressiveness of this cancer." (PMID 33513799, 2021). "FDPS is a key enzyme in cholesterol biosynthesis and has been found to play an important role in the development of several malignant tumors." (PMID 40839681, 2025). "For instance, FDPS is involved in cholesterol biosynthesis and prenylation, processes vital for cell functions often exploited by cancer cells." (PMID 39272878, 2024). "Studies have shown that knockdown FDPS enhanced apoptosis and ectopic overexpression of FDPS promoted cancer colony growth and proliferation by affecting STAT3, AKT and ERK pathways." (PMID 36634566, 2023). "We conclude that inhibition of farnesyl diphosphate synthase by zoledronic acid offers a promising strategy to increase the efficacy of statins in cancer patients." (PMID 28808351, 2017). "One enzyme (farnesyl diphosphate synthase FDPS) from the terpenoid biosynthesis pathway (1 out of 15 enzymes) that feeds in N-glycan biosynthesis pathway was also overexpressed in cancer." (PMID 25243088, 2014). "We detected in PR elevated levels of enzymes (COX-2, ACSS2, FDPS, FASN, ACAT2, ACLY, SLC12A2) and metabolites (arachidonic acid and carnitine) involved in lipid metabolism, which have been linked to radioresistance of cancer cells." (PMID 38410100, 2024). "Current N-BP drugs are attractive and promising FDPS inhibitors in cancer treatment." (PMID 35625883, 2022). "Our data show that chronic RT of PDAC cells results in upregulation of FDPS, cyclin D1, cyclin B1, and cancer stem cell markers in PDAC cells accompanied by altered cellular morphology, increased survival facilitated by G2/M arrest, and an increased side population." (PMID 34971971, 2022). "In vitro and in vivo antitumor effect of IPA have been commonly, but not exclusively, associated with FDPS inhibition, a key enzyme involved in mevalonate pathway—responsible for cholesterol biosynthesis and protein prenylation—widely involved in cancer." (PMID 31569395, 2019). "The FDPS is upregulated in some cancers resulting in resistance to aminobisphosphonate drugs." (PMID 29937769, 2018). "Numerous enzymes within the MVA are frequently upregulated in cancer, including HMGCR, farnesyl diphosphate synthase (FDPS), geranylgeranyl pyrophosphate synthase (GGPPS), squalene synthase (SS), and SQLE." (PMID 39969135, 2025). "Our study indicates upregulation of multiple genes that are particularly enzymes involved in cholesterol biosynthesis, i.e., GGPS1, SQLE, FDPS, HMGCS1, and HMGCR, which were also reported in distinct cancer models." (PMID 35050168, 2022). "Many enzymes of the MVA are often overexpressed in cancer, including HMGCR, farnesyl diphosphate synthase (FDPS), geranylgeranyl pyrophosphate synthase (GGPPS), squalene synthase, and squalene epoxidase." (PMID 33946927, 2021). "Acting on the mevalonate pathway to reduce secondary metabolites and ultimately counteract the activities of FDPS and NME1 looks attracting as a novel cancer therapy, in agreement with several data." (PMID 28962550, 2017).
cancer (continued). "Moreover, inhibition of specific enzymes involved in cholesterol metabolism, including lanosterol synthase (LSS), farnesyl diphosphate synthase (FDPS), and squalene epoxidase (SQLE), has been shown to suppress cancer metastasis." (PMID 38762737, 2024). "FDPS is a second key regulatory point of the targeted MVA pathway; small molecules targeting the FDPS signaling pathway have emerged as a promising therapeutic approach for numerous cancers." (PMID 35625883, 2022). "In addition, FDPS is a critical gene involved in CBS and is required for the isoprenylation of Rho GTPase Rac1, which drives K-Ras-driven cancers." (PMID 34971971, 2022). "However, cancer cells eventually acquire radioresistance (RR) through metabolic reprogramming of cholesterol biosynthesis pathway (CBS) genes, specifically, farnesyl diphosphate synthase (FDPS)." (PMID 34971971, 2022). "Mechanistically, HMGCR or FDPS depletion impaired cancer stemness characteristics by activating TGF-β signaling, which in turn downregulated expression of inhibitors of differentiation (ID) proteins, key regulators of cancer stemness." (PMID 34621019, 2021). "Other small molecule inhibitors of mevalonate pathway targeting farnesyl diphosphate synthase (FPPS) and geranylgeranyl diphosphate synthase (GGPPS) like the nitrogen-containing bisphosphonates (N-BPs) and their analogues have been studied in the setting of lytic bone disease and cancer." (PMID 39026984, 2024).
infection (7 papers, 2013 to 2024). The state of being infected such as from the introduction of a foreign agent such as serum, vaccine, antigenic substance or organism. "The infection of A. sinensis callus tissue with Phaeoacremonium rubrigenum induced a significant upregulation of farnesyl diphosphate synthase (FPS) gene expression, Ses TPS1 and Ses TPS2, which confirmed that the fungi primarily induced the biosynthesis of terpenes through the MVA pathway." (PMID 39628533, 2024). "Expression of IDS1, a bi-functional geranyl diphosphate and geranylgeranyl diphosphate synthase, IDS4, a farnesyl diphosphate synthase, and IDS5, a geranyl diphosphate synthase, increased significantly upon infection except for IDS1 and IDS4 in PA trees." (PMID 35599904, 2022).
endocrine system disorder (1 paper, 2010). A disease involving the endocrine system. "IPA data base showed RETNLB and FDPs were associated with endocrine system disorders; CAPG, ACOT9, FDPS, and IMPDH2 were associated with genetics disorder." (PMID 21172007, 2010).
FDPS also shares sentences with these, for which no sentence is quoted: cardiac hypertrophy (4 papers); diabetes (3); non-small cell lung carcinoma (3); pancreatic ductal adenocarcinoma (3); atherosclerosis (2); bone cancer (2); bone resorption disease (2); brain cancer (2); Chagas disease (2); esophageal cancer (2); Hypercalcemia (2); hyperlipidemia (2); acute myeloid leukemia (1); Alzheimer disease (1); American trypanosomiasis (1); bladder cancer (1); cardiovascular diseases (1); emphysema (1); gastric adenocarcinoma (1); Granuloma (1); head and neck squamous cell carcinoma (1); heart disease (1); Insulin resistance (1); leishmaniasis (1); leukemia (1); lung adenocarcinoma (1); metastatic tumors (1); multiple myeloma (1); myeloid leukemia (1); neoplastic disorders (1).
A further 17 diseases each share a sentence with FDPS in 1 paper.